SRP68 (signal recognition particle 68)
Description:
Component of the signal recognition particle (SRP) complex, a ribonucleoprotein complex that mediates the cotranslational targeting of secretory and membrane proteins to the endoplasmic reticulum (ER). The SRP complex interacts with the signal sequence in nascent secretory and membrane proteins and directs them to the membrane of the ER. The SRP complex targets the ribosome-nascent chain complex to the SRP receptor (SR), which is anchored in the ER, where SR compaction and GTPase rearrangement drive cotranslational protein translocation into the ER. Binds the signal recognition particle RNA (7SL RNA), SRP72 binds to this complex subsequently. The SRP complex possibly participates in the elongation arrest function (By similarity).
Synonyms: SCN10
Tractability: Small molecule: a structure with a bound ligand is known. PROTAC: ubiquitination databases record sites on it; its protein half-life has been measured.
Gene: Protein-coding gene on chromosome 17 (76,038,775 to 76,072,517, reverse strand). Ensembl gene ENSG00000167881.
Subcellular location: Cytoplasm; Nucleus, nucleolus; Endoplasmic reticulum
Subcellular location (Human Protein Atlas): Cytosol
Pathways (Reactome):
Metabolism of proteins: SRP-dependent cotranslational protein targeting to membrane
Gene Ontology:
Molecular function: 7S RNA binding; protein binding; protein domain specific binding; ribosome binding; RNA binding; signal recognition particle binding; endoplasmic reticulum signal peptide binding
Biological process: response to xenobiotic stimulus; SRP-dependent cotranslational protein targeting to membrane; SRP-dependent cotranslational protein targeting to membrane, signal sequence recognition
Cellular component: cytoplasm; cytosol; endoplasmic reticulum; signal recognition particle; signal recognition particle, endoplasmic reticulum targeting; nucleolus; ribosome
Genetic constraint (gnomAD): Loss-of-function variants: 15 observed, 68.94 expected, observed/expected ratio (o/e) 0.22, 90% interval 0.14 to 0.34. The upper end of that interval is the gene's LOEUF score, 0.34, which puts it in group 1 of 6, group 1 being the genes least tolerant of losing a copy. Missense variants: 543 observed, 734.64 expected, observed/expected ratio (o/e) 0.74, 90% interval 0.69 to 0.79. Synonymous variants: 245 observed, 281.96 expected, observed/expected ratio (o/e) 0.87, 90% interval 0.78 to 0.97.
Homologues: Orthologues: macaque SRP68 (99% identical), chimpanzee SRP68 (98% identical), dog SRP68 (97% identical), rabbit SRP68 (95% identical), mouse Srp68 (95% identical), pig SRP68 (95% identical), guinea pig SRP68 (95% identical), rat Srp68 (95% identical), tropical clawed frog srp68 (79% identical), zebrafish srp68 (71% identical), Drosophila melanogaster Srp68 (40% identical), Caenorhabditis elegans srpa-68 (30% identical).
Diseases named in the same sentence as SRP68 in open-access papers:
SRP68 is named in the same sentence as 9 diseases in open-access papers, as found by Europe PMC text mining. Sharing a sentence is not in itself a finding about the gene and the disease. The quoted sentences say what the papers report.
autoimmune disease (1 paper, 2021). A disorder resulting from loss of function or tissue destruction of an organ or multiple organs, arising from humoral or cellular immune responses of the individual to their own tissue constituents. "In addition, Ku80 and nucleolin are important autoantigens in patients with systemic lupus erythematosus and other systematic autoimmune disorders, suggesting a potential implication of SRP68/72 associated with the 500-kDa complex in autoimmune diseases." (PMID 34113652, 2021). "Another interesting noncanonical function that could be targeted is the interaction of nucleolin with the heterodimer SRP68/72 for cancer therapies and autoimmune diseases." (PMID 34113652, 2021).
Smith-Magenis syndrome (1 paper, 2021). Smith-Magenis syndrome (SMS) is a complex genetic disorder characterized by variable intellectual deficit, sleep disturbance, craniofacial and skeletal anomalies, psychiatric disorders, and speech and motor delay. "Three pseudogenes of Srp68 gene are located within the Smith-Magenis syndrome (SMS) region on chromosome 17." (PMID 34113652, 2021).
cancer (2 papers, 2021 to 2025). A tumor composed of atypical neoplastic, often pleomorphic cells that invade other tissues. "SRP68/72 heterodimer associates with cell-surface nucleolin in a stable 500-kDa protein complex that includes proteins involved in cancer progression, such as nucleophosmin (NPM1), Wnt-1, the antigen Ku80 and C1q-R, as well as the ribosomal proteins S4 and S6." (PMID 34113652, 2021). "The discovery of the primary hydrophobic, concave bonding region on SRP72 linked to SRP68 opens doors for the creation of compounds that could be utilized in treating cancer." (PMID 40042106, 2025).
infection (1 paper, 2024). The state of being infected such as from the introduction of a foreign agent such as serum, vaccine, antigenic substance or organism. "SRP68 and PLSCR1 implicate ongoing cellular adjustments in response to infection stress." (PMID 38655085, 2024).
tumor (1 paper, 2022). "SRP68 is a key component of SRP ribonucleoprotein complex regulating endoplasmic reticulum trafficking for protein export and tumor cell mobility." (PMID 35402263, 2022).
SRP68 also shares sentences with these, for which no sentence is quoted: bladder cancer (1 paper); dilated cardiomyopathy (1); neurodevelopmental disorder (1); urothelial carcinoma (1).